MIR379 (microRNA 379)
Synonyms: hsa-mir-379; MIRN379; mir-379
Gene: MicroRNA gene on chromosome 14 (101,022,066 to 101,022,132, forward strand). Ensembl gene ENSG00000199088.
Homologues: Orthologues: chimpanzee ptr-mir-379 (100% identical).